SMAD5-AS1 (SMAD5 antisense RNA 1)
Synonyms: DAMS; SMAD5OS; SMAD5AS
Gene: Long non-coding RNA gene on chromosome 5 (136,129,504 to 136,134,890, reverse strand). Ensembl gene ENSG00000164621.
Diseases named in the same sentence as SMAD5-AS1 in open-access papers:
SMAD5-AS1 is named in the same sentence as 1 disease in open-access papers, as found by Europe PMC text mining. Sharing a sentence is not in itself a finding about the gene and the disease. The quoted sentences say what the papers report.
nasopharyngeal carcinoma (1 paper, 2019). A carcinoma arising from the nasopharyngeal epithelium. "Differentially expressed lncRNA SMAD5 antisense RNA 1 (SMAD5-AS1) in nasopharyngeal carcinoma (NPC) and normal samples shown by in silico analyses were selected as the main subject, and then microRNA-195 (miR-195) was suggested to bind to SMAD5-AS1 and SMAD5." (PMID 31921616, 2019).